GTSE1 (G2 and S-phase expressed 1)
Diseases named in the same sentence as GTSE1 in open-access papers (continued):
Sharing a sentence is not in itself a finding about the gene and the disease.
triple-negative breast carcinoma (4 papers, 2017 to 2022). An invasive breast carcinoma which is negative for expression of estrogen receptor (ER), progesterone receptor (PR), and human epidermal growth factor receptor 2 (HER2). "The aims of this work were to elucidate how GTSE1 is regulated at the transcriptional level and to clarify the mechanism underlying GTSE1-dependent cell functions in triple-negative breast cancer (TNBC)." (PMID 28978043, 2017). "As a target gene of the TEAD4 transcription factor, GTSE1, which transcriptional regulation related to the YAP and TAZ coactivator, plays an important role in triple-negative breast cancer." (PMID 31781484, 2019).
bladder cancer (3 papers, 2023 to 2024). "Liu and colleagues reveal that knockdown of GTSE1 reduces the expression of FOXM1 and CCNB1 in bladder cancer, indicating that GTSE1 positively modulates the expression and level of FOXM1." (PMID 38698443, 2024). "Moreover, GTSE1 is identified to participate in the proliferation, migration, and invasion of bladder cancer." (PMID 38698443, 2024).
cervical cancer (3 papers, 2015 to 2024). A primary or metastatic malignant neoplasm involving the cervix. "The results revealed upregulation of GTSE1 in 19 tumor tissues, including cervical cancer, suggesting its potential as a common biomarker for multiple tumors." (PMID 38715380, 2024).
head and neck squamous cell carcinoma (3 papers, 2023 to 2024). A squamous cell carcinoma that arises from any of the following anatomic sites: lip and oral cavity, nasal cavity, paranasal sinuses, pharynx, larynx, and salivary glands. "Interestingly, head and neck squamous cell carcinoma (HNSCC), acute myeloid leukemia (LAML), and lung squamous cell carcinoma (LUSC) showed higher expression levels of GTSE1 in males compared to females." (PMID 38715380, 2024). "In HNSCC (head and neck squamous cell carcinoma), LAML (acute myeloid leukemia), and LUSC (lung squamous cell carcinoma), male patients exhibited higher levels of GTSE1 expression compared to female patients." (PMID 38715380, 2024).
breast invasive carcinoma (2 papers, 2017 to 2024). "Moreover, GTSE1 expression levels associate with invasive potential and tumour grade, with higher protein levels in the most aggressive and invasive breast cancer cell lines." (PMID 28978043, 2017).
breast tumors (2 papers, 2019 to 2023). "We performed the χ2 test, which demonstrated that the increased GTSE1 expression in primary breast tumors were significantly related to a higher histological grade (p = 0.0024)." (PMID 30961661, 2019).
COVID-19 (2 papers, 2021 to 2024). A disease caused by infection with severe acute respiratory syndrome coronavirus 2. "To identify potential drugs for the treatment of COVID-19 and KIRC co-morbidity, we conducted drug target enrichment analysis with four hub genes (GTSE1, CEACAM4, HECW2, and KCNMA1) as genetic targets associated with the construction of risk models via cellMiner and DsigDB databases." (PMID 38464749, 2024). "In this study, we identified 156 shared genes between the COVID-19 and KIRC cohorts and selected four hub genes (GTSE1, CEACAM4, HECW2, and KCNMA1) as the foundation for developing a risk model." (PMID 38464749, 2024).
endometrial cancer (2 papers, 2019 to 2021). Primary or metastatic malignant neoplasm involving the endometrium (mucous membrane that lines the endometrial cavity). "The K-M plots showed that, except GTSE1, all genes were significantly associated with endometrial cancer patients' prognosis." (PMID 31781484, 2019). "Moreover, the data also shows that the higher expression of AKT1, GTSE1, BIRC5, AURKA, and KNSTRN is significantly associate with poor prognosis of endometrial cancer." (PMID 31781484, 2019). "In addition, the data also shows that the higher expression of AKT1, GTSE1, BIRC5, AURKA, and KNSTRN is significantly associate with poor prognosis of endometrial cancer." (PMID 31781484, 2019). "We selected the six hub genes (GTSE1, BIRC5, AURKA, PBK, KNSTRN, and PSMB10) and AKT1 to evaluate gene expression values in endometrial cancer using IHC." (PMID 31781484, 2019).
esophageal carcinoma (2 papers, 2023 to 2024). A primary or metastatic malignant neoplasm involving the esophagus. "Moreover, younger patients (<65 years old) with BRCA, esophageal carcinoma (ESCA), KIRP, LIHC, LUAD, PCPG, and READ had higher levels of GTSE1 expression in cancer tissues (p < 0.05)." (PMID 38715380, 2024).
lung fibrosis (2 papers, 2019 to 2023). "Immunofluorescence analysis using mouse fibrotic lung tissues suggested that fibrotic regions showed increased expressions of Gtse1 and Fgl1, indicating novel molecular signatures of gtse1and fgl1 for IR-induced lung fibrosis." (PMID 30406363, 2019). "Although further functional analyses are required to determine the roles of GTSE1 or FGL1 during development of lung fibrosis, our results might provide the information that is useful for understanding IR-induced lung fibrosis." (PMID 30406363, 2019).
melanoma (2 papers, 2020 to 2021). A malignant, usually aggressive tumor composed of atypical, neoplastic melanocytes. "ITGA2 plays a role in melanoma by regulating the expression GTSE1, thereby restoring the epithelial-to-mesenchymal transition in SKCM." (PMID 34660316, 2021).
neuroendocrine tumors (2 papers, 2016 to 2021). "Higher GTSE1 expression is associated with more aggressive phenotypes in neuroendocrine tumors." (PMID 27240802, 2016). "In neuroendocrine tumors, overexpression of GTSE1 can augment aggressive phenotypes." (PMID 34007784, 2021).
sarcoma (2 papers, 2021 to 2024). A usually aggressive malignant neoplasm of the soft tissue or bone. "However, male patients with KIRP, LIHC, and SARC (sarcoma) had reduced levels of GTSE1 expression (p < 0.05)." (PMID 38715380, 2024). "The GEPIA data suggested that GTSE1 was highly expressed in patients with sarcoma." (PMID 34876170, 2021).
bladder urothelial carcinoma (1 paper, 2024). "Notable disparities were observed in 19 tumor types, such as bladder urothelial carcinoma, where the mRNA expression level of GTSE1 was higher among cancer tissues compared to the control tissues with statistical significance (p < 0.05)." (PMID 38715380, 2024).
familial cancers (1 paper, 2021).
gastroenteropancreatic neuroendocrine tumors (1 paper, 2012). "More recently, GTSE1 was identified as one of three cell cycle regulatory genes (along with CDKN3 and Cyclin B1) whose upregulation in gastroenteropancreatic neuroendocrine tumors correlate with metastasis." (PMID 23236459, 2012).
liver disease (1 paper, 2022). "The persistently affected genes Lama5, Gtse1, Fabp4, and Bcl6 possess the potential to be therapeutic targets for liver disease induced by AFB1." (PMID 35783385, 2022). "The persistently affected Lama5, Gtse1, Fabp4 and Bcl6 gene can be potential target genes for the treatment of AFB1 induced liver diseases, but their effectiveness needs to be further explored in experiments." (PMID 35783385, 2022).
lymph node metastasis (1 paper, 2023). "Briefly, higher GTSE1 expression correlated with more lymph node metastasis, advanced clinical stages, and higher tumor grades." (PMID 36999057, 2023). "There was a positive correlation between GTSE1 expression and tumor stage, lymph node metastasis, distant organ metastasis, pathologic stage, and histologic grade." (PMID 36999057, 2023).
neuroblastoma (1 paper, 2017). Neuroblastoma (NB) is the most common solid, extracranial childhood tumor. "Interestingly, the downregulation of 45A ncRNA strongly affects the in vivo tumorigenic potential of SKNBE2 neuroblastoma cells, increasing tumor nodule compactness and reducing GTSE1 protein expression in a subcutaneous neuroblastoma mouse model." (PMID 28029658, 2017).
squamous cell carcinoma (1 paper, 2021). A carcinoma arising from squamous epithelial cells. "In addition, AREG upregulated samples were enriched in the pathways of protein G-2 and S-phase expressed 1 (GTSE1) in G2/M progression after the G2 checkpoint, and associated with genes up-regulated in SCC12B2 cells (squamous cell carcinoma) by ultraviolet B (UV-B) irradiation." (PMID 33712015, 2021).
stomach adenocarcinoma (1 paper, 2024). "Patients with BRCA and seven other forms of carcinoma under the age of 65 exhibited higher GTSE1 expression levels, whereas young patients with gastric adenocarcinoma had lower levels of GTSE1." (PMID 38715380, 2024). "Conversely, STAD (stomach adenocarcinoma) showed lower levels of GTSE1 in younger patients (<65 years old) (p < 0.05)." (PMID 38715380, 2024).
cancer (38 papers, 2012 to 2025). A tumor composed of atypical neoplastic, often pleomorphic cells that invade other tissues. "Functionally, the phosphorylation of GTSE1 promotes cellular proliferation and is associated with poor prognosis within a pan-cancer cohort." (PMID 38979260, 2025). "GTSE1, which is highly expressed in various cancers, including PCa, and linked to poor prognoses, promotes PCa cell proliferation by activating the SP1/FOXM1 signaling pathway." (PMID 40626556, 2025). "Using ROC curves, we evaluated the diagnostic sensitivity and specificity of GTSE1, which effectively distinguished cancer tissues from normal tissues in 21 types of tumors with high diagnostic efficiency." (PMID 38715380, 2024). "The aim of this study was to comprehensively analyze the degree of GTSE1 expression, along with its diagnostic and prognostic value in 33 types of malignant tumors, as well as its correlation with immune invasion using gene expression profiles." (PMID 38715380, 2024). "GTSE1 has been implicated in various malignant tumors, including osteosarcoma, BRCA, and colon cancer, regarding their occurrence, development, and prognosis." (PMID 38715380, 2024). "The study explored GTSE1 expression levels, diagnostic and prognostic significance, and its association with immune infiltration across 33 cancer types." (PMID 38715380, 2024). "The association between GTSE1 expression and the prognosis of cancer patients suggests further analysis of its correlation with patient prognosis." (PMID 38715380, 2024). "In summary, GTSE1 showed a potential as a diagnostic and prognostic biomarker for various types of cancers." (PMID 38715380, 2024). "Despite the extensive research on pan‐cancer in the past 5 years, the association between GTSE1 and various malignant tumors remains unexplored." (PMID 38715380, 2024). "Our analysis identified several previously known carcinogenic L1 ASP-associated genes, such as MMP1 and GTSE1, which were up regulated in multiple cancer types." (PMID 37723560, 2023). "Future studies should attempt to clarify the underlying mechanism of GTSE1 together with minichromosome-related protein-mediated DNA replication and cancer prognosis." (PMID 32082966, 2019). "In spite of the rising interest about GTSE1 and its role in cancer progression, its transcriptional regulation and the causes of its deregulation in cancer remain poorly understood." (PMID 28978043, 2017). "GTSE1 is highly expressed in cancers and was shown to be clinically associated with drug resistance." (PMID 26209226, 2015). "Moreover, our inquiry not only scrutinizes the interplay among GTSE1 expression, prognosis, and immune infiltration in pan‐cancer contexts but also discloses, for the inaugural time, the heightened diagnostic efficacy of GTSE1 across 21 distinct cancer types." (PMID 38715380, 2024). "Finally, the pan‐cancer analysis findings were validated by examining the association between GTSE1 expression and prognosis among patients with LUAD." (PMID 38715380, 2024). "Therefore, we investigated the diagnostic value of GTSE1 as an independent pan‐cancer biomarker." (PMID 38715380, 2024). "Recent research has underscored the significant role of GTSE1 in various cancers, including lung, liver, and gastric cancers." (PMID 40710178, 2025). "Members of the E2F family, which were overexpressed in GTSE1+ OB cells, play important roles in DNA repair and cancer metastasis." (PMID 40831537, 2025). "Our findings demonstrate that the cyclin D1-CDK4/6-mediated phosphorylation of GTSE1 leads to its increased stability in G1 phase, an event that significantly impacts cell proliferation and cancer prognosis." (PMID 38979260, 2025). "The CPTAC datasets used in this study include pan-cancer proteomic data referenced for the analysis of GTSE1 phosphorylation levels across multiple cancer types." (PMID 40272409, 2025).
cancer (continued). "PaganoM2025Stabilization of GTSE1 by cyclin D1-CDK4/6-mediated phosphorylation promotes cell proliferation: relevance in cancer prognosisMendeley Data10.17632/xzkw7hrwjr." (PMID 40272409, 2025). "The upregulation of GTSE1 protein in cancer samples was further confirmed in 111 pairs of LUAD samples obtained from the CPTAC database." (PMID 39629227, 2024). "In the ROC analysis of individual tumor types, AUC > 0.7 was observed for 19 types of cancer, indicating that GTSE1 mRNA expression levels are highly potential to differentiate cancer tissues from control tissues in these tumors." (PMID 38715380, 2024). "Specifically, we elucidate, for the first time, disparities in the expression profiles of GTSE1 across diverse cancer types concerning clinical parameters, thus providing substantive implications for tailored cancer therapeutics." (PMID 38715380, 2024). "Lastly, although pan‐cancer analysis results supported the relationship of GTSE1 expression and immune regulation mechanisms, further exploration is of necessity to thoroughly understand its underlying mechanisms." (PMID 38715380, 2024). "The findings revealed distinct GTSE1 expression levels among different cancer tissues in contrast with control tissues." (PMID 38715380, 2024). "In non‐diploid carcinoma cell lines and tumors, overexpression of GTSE1 regulates MT stability during mitosis by inhibiting the activity of MCAK, an MT depolymerase enzyme." (PMID 38715380, 2024). "GTSE1 mRNA expression was investigated across cancers using the TIMER 2.0 web tool and the UALCAN web tool." (PMID 36999057, 2023). "GTSE1 regulates the G1/S cell cycle transition and has been reported to be overexpressed in other human cancers." (PMID 35456486, 2022). "It has been reported that the high GTSE1 expression contributes to the malignant behavior of human cancer." (PMID 34007784, 2021). "Yet, the mapped genes were highly relevant to PCa etiology and included known cancer drivers LDLRAD4, GMNN, COL1A1, CD38, PTPRN2, GTSE1 and CAMK2N1 in the risk signature and KLK2, AR, KLK3, SPDEF in the relapse signature." (PMID 33845808, 2021). "High GTSE1 expression was then detected in clinically collected OS tissues and the procured OS cell lines, preliminarily indicating its involvement in cancer progression." (PMID 34876170, 2021). "Some studies further reported that upregulation of GTSE1 was frequently found in several types of human cancers." (PMID 34007784, 2021). "A previous study has shown that the G2 and S phase-expressed-1 (GTSE1) can act as an oncogene in several human cancers." (PMID 30961661, 2019). "The paclitaxel sensitivity of cancer cells and cisplatin-induced cell death was enhanced after silencing the expression of GTSE1." (PMID 31781484, 2019). "GTSE1 binds to the microtubule plus-end tracking protein EB1 in cancer and regulates microtubule stability for accurate chromosome alignment and segregation." (PMID 32082966, 2019). "GTSE1 has been demonstrated as a potential biomarker for poor clinical outcome in several types of cancer." (PMID 32082966, 2019). "We and others reported that GTSE1 promotes different aspects of cancer progression including chemoresistance, chromosome instability (CIN) and metastasis." (PMID 28978043, 2017).